IRF3 (interferon regulatory factor 3)
Diseases named in the same sentence as IRF3 in open-access papers (continued):
Sharing a sentence is not in itself a finding about the gene and the disease.
mesothelioma (1 paper, 2021). A usually malignant and aggressive neoplasm of the mesothelium which is often associated with exposure to asbestos. "In this study, we evaluated the tumor growth of various murine mesothelioma cell lines in wild-type (WT) compared to IRF3 knockout (IRF3KO) mice." (PMID 34768716, 2021). "IRF3 expression and the immune checkpoint genes significantly correlated with LAG3 and LGALS1 (Galectin) genes expression in mesothelioma cells, while positive correlation was found between IRF3 and HAVCR2 (TIM-3) or PDCD1LG2 (PD-L2) expression in monocytes/macrophages." (PMID 34768716, 2021). "Our results indicate that IRF3 may play critical roles in the immunosuppressive microenvironment of mesothelioma." (PMID 34768716, 2021). "IRF3 may be used as potential targets for therapeutics and prognosis in mesothelioma." (PMID 34768716, 2021). "Strikingly, IRF3 and LGALS1 (Galectin-1) genes were highly expressed in both murine and human mesothelioma cells." (PMID 34768716, 2021). "Dotplot of IRF3 and the cGAS/STING signaling pathway genes showed that IRF3 and STING (TMEM173) were expressed in mesothelioma tumor cells, while TBK1 and CGAS expressed mainly in monocyte/macrophages." (PMID 34768716, 2021). "Correlation of IRF3 with the immune checkpoints in TCGA MESO and coexpression with LGALS1 in scRNA-Seq data from our patient samples imply that IRF3 may be an inhibitory transcription regulator in mesothelioma." (PMID 34768716, 2021).
microcephaly (1 paper, 2023). A congenital or acquired developmental disorder in which the circumference of the head is smaller than normal for the person's age and sex. "At the protein level, we also verified a decreased RIG-I and IRF-3 expression in the decidual placenta from the Zika-infected obese group, regardless of microcephaly." (PMID 36851534, 2023).
mucopolysaccharidoses (1 paper, 2021). "GSEA demonstrated that mucopolysaccharidoses, the butyrophilin BTN family, the EGFR/SMRTE pathway, IRF3- mediated induction of type I INF, FOXO-mediated transcription of cell cycle genes, and the ERK pathway were differentially enriched in association with high levels of CYBRD1 expression." (PMID 34594380, 2021).
nasal polyps (1 paper, 2022). "Our results showed that PVP-I can inhibit the inflammation-induced IL-1β secretion and IRF3/7 activation, and 27 cytokines in airway epithelial cells and pHNECs from nasal polyps." (PMID 35256715, 2022).
Newcastle disease (1 paper, 2007). A condition caused by infection by the Newcastle disease virus, which may be characterized by conjunctivitis, respiratory illness, and diarrhea. "IRF-3 has been previously shown to contribute to an antiviral state by activating ISGs, including ISG54 and ISG56, in an IFN-dependent and -independent manner in fibroblasts and epithelial cells infected with HSV, VSV, Newcastle disease, vaccinia, and Sendai viruses." (PMID 17676997, 2007).
non-alcoholic steatohepatitis (1 paper, 2020). "In a non-alcoholic steatohepatitis (NASH) model induced by a methionine- and choline-deficient or high-fat diet, lipotoxicity can cause mitochondrial damage and up-regulate STING/IRF3 expression in hepatocytes, which in turn promotes lipid accumulation and inhibits glycogen synthesis." (PMID 32411126, 2020).
non-melanoma skin carcinoma (1 paper, 2021). "IRF3 (interferon regulatory factor 3), for example, is associated with non-melanoma skin cancer according to PWAS with overwhelming significance (FDR q-value = 7E−6), but not according to GWAS (p = 1E−6)." (PMID 34290314, 2021).
Opportunistic infection (1 paper, 2010). An infection that is caused by a pathogen that would generally not be able to cause an infection in a host with a normal immune system. "IRF3-depletion was dependent on a productive HIV replication cycle and caused disruption of IRF3-mediated signalling pathways, including TLRs and RLRs, in this manner promoting host cell permissiveness for infection with both HIV and opportunistic infections." (PMID 20569472, 2010).
oral cancer (1 paper, 2019). "Another study showed that exosomal nuclear factor-κB-activating kinase-associated protein 1 (NAP1) derived from oral cancer promotes the cytotoxicity of natural killer (NK) cells via activation of the interferon regulatory factor (IRF-3) signaling pathway in recipient cells." (PMID 31620359, 2019).
parvovirus infection (1 paper, 2023). "Altogether, our data clearly indicate that during a productive parvovirus infection both transcription factors, NFĸB and IRF3, translocate into the nucleus of infected cells and activate an upstream PRR-dependent pathway." (PMID 37111493, 2023). "Since this evasion mechanism is able to block both RLR-dependent (NDV infection or poly(I:C) transfection) and RLR-independent (parvovirus infection) IFN production, it appears to act at a step shared by several IFN-inducing pathways and one downstream of IRF3 and NFκB nuclear translocation." (PMID 37111493, 2023).
periodontal disease (1 paper, 2021). "Current studies produced evidence for using STING-pathway-targeting molecules as part of anticancer therapy, and as vaccine adjuvants against microbial infections; however, the role of the STING/TBK1/IRF3 pathway in periodontal disease pathogenesis is still undiscovered." (PMID 34070809, 2021).
periodontitis (1 paper, 2021). An acute or chronic inflammatory process that affects the tissues that surround and support the teeth. "PubMed/Medline, Scopus, and Web of Science were searched with the terms “STING”, “TBK 1”, “IRF3”, and “cGAS”—alone, or together with “periodontitis”." (PMID 34070809, 2021). "The literature was searched using the terms “STING”, “STING and periodontitis”, “TBK1”, “TBK 1 and periodontitis”, “IRF3”, “IRF3 and periodontitis”, “cGAS”, and “cGAS and periodontitis” by S.E. and M.Y., using the databases of PubMed/Medline, Scopus, and Web of Science." (PMID 34070809, 2021). "Moreover, IRF3 accumulated close to the basement membrane in the gingival tissues of periodontitis patients." (PMID 34070809, 2021).
pestivirus infection (1 paper, 2013). "Npro binds interferon regulatory factor-3 (IRF3), the key transcriptional activator of IFN-α/β genes, and promotes degradation of IRF3 by the proteasome, thus preventing induction of the IFN-α/β response to pestivirus infection." (PMID 24146623, 2013).
plague (1 paper, 2012). Plague is a severe bacterial infection caused by the gram-negative bacterium Yersinia pestis. "We show that the respiratory pathogen, Yersinia pestis, the causative agent of plague, activates IRF-3 and the IFN-I response and that these two events cause opposite outcomes in the host." (PMID 22911267, 2012). "IRF-3, however, was necessary for host defense and its expression led to decreased susceptibility to plague in a manner that correlated with decreased bacterial growth." (PMID 22911267, 2012). "Bacterial colonies could be seen in some areas of necrosis in the liver of mutant mice and these appeared larger and more numerous as disease progressed suggesting that rapid bacterial growth caused accelerated plague in the Irf3−/− mice." (PMID 22911267, 2012). "Intranasal infection of the wild type Y. pestis strain KIM5 leads to primary pneumonic plague over a period of 3–4 days, and Irf3−/− mice succumbed to disease with an indistinguishable time course and mortality rate." (PMID 22911267, 2012).
poliovirus infection (1 paper, 2015). An disease or disorder caused by infection with Enterovirus C. "The results demonstrate that poliovirus infection results in the activation of both ATF-2 and NF-κB but very little activation of IRF-3." (PMID 26437794, 2015). "Collectively, these results demonstrate that poliovirus infection actively suppresses the host type I interferon response by blocking activation of IRF-3 and suggests that this is not mediated by cleavage of MDA-5 or IPS-1." (PMID 26437794, 2015).
preeclampsia (1 paper, 2025). Preeclampsia is a hypertensive disorder of pregnancy that is characterized by new-onset hypertension with proteinuria presenting after 20 weeks of gestation, and depending on mild or severe forms may initially present with severe headache, visual disturbances, and hyperreflexia. "Further analysis of gene regulatory networks, including transcription factor–gene, gene–microRNA, and drug–gene interactions, revealed that seven hub genes (HK2, SRSF10, SOD1, ERO1L, IRF3, MME, and SH3BP5) were strongly associated with preeclampsia." (PMID 40966654, 2025). "Constructed a protein–protein interaction (PPI) network, identifying 10 hub genes, seven of which (HK2, SRSF10, SOD1, ERO1L, IRF3, MME, and SH3BP5) were strongly linked to preeclampsia." (PMID 40966654, 2025).
prion disease (1 paper, 2014). A transmissible disease that is caused by a protein that is able to induce abnormal folding of normal cellular proteins, leading to characteristic spongiform brain changes, which are associated with neuronal loss without an inflammatory response. "IRF3, on the other hand, may be activated by irregular protein structure or function, based on an Irf3 knockout mouse model that succumbs to prion diseases more rapidly than the control cohort." (PMID 24762633, 2014).
pulmonary fibrosis (1 paper, 2021). Chronic progressive interstitial lung disorder characterized by the replacement of the lung tissue by connective tissue, leading to progressive dyspnea, respiratory failure, or right heart failure. "As downstream signaling pathways of TLR4, MAPK family, NF-κB and IRF3 have been reported to regulate cell growth and inflammation, leading to pulmonary fibrosis 74-76." (PMID 33746598, 2021).
pyometra (1 paper, 2016). "Constitutive transcription of MyD88-dependent (MyD88, TRAF6, NFKβ) and independent (TRAM, TRIF, IRF3) pathway components was detected in healthy diestrous and pyometra endometria." (PMID 27829462, 2016).
respiratory infections (1 paper, 2019). "The airway epithelium is a major target tissue in respiratory infections, and its antiviral response is mainly orchestrated by the interferon regulatory factor-3 (IRF3), which subsequently induces type I (β) and III (λ) interferon (IFN) signalling." (PMID 31319869, 2019).
retinal degeneration (1 paper, 2021). Degeneration of the retina. "By using siRNAs against TLR and IRF3 in AMD disease, TLR induced apoptosis and retinal degeneration by initiating the caspase pathway, but this was not confirmed in IRF3." (PMID 34646884, 2021).
severe combined immunodeficiency (1 paper, 2022). Severe combined immunodeficiency (SCID) comprises a group of rare monogenic primary immunodeficiency disorders characterized by a lack of functional peripheral T lymphocytes resulting in early-onset severe respiratory infections and failure to thrive. "Heterozygous N153S and V154M mouse strains display lymphopenia and developed IRF3- and type I IFNs-independent severe combined immunodeficiency disease (SCID) occurring early in thymic development." (PMID 36359882, 2022).
skin infection (1 paper, 2020). An inflammatory process affecting the skin, caused by bacteria, viruses, parasites, or fungi. "Corroborating in vitro data, Myd88−/− knockout mice downregulated TNF, CXCL1; and phospho-p65 and phospho-IRF3 nuclear localization, upon poly I:C treatment in a mouse model of skin infection." (PMID 32824595, 2020). "We adopted a well-known mouse model of skin infection to look at the expression of pro-inflammatory genes TNF and CXCL1 and the transcriptional factors NF-κB and IRF3 after the treatment with poly I:C or the vehicle." (PMID 32824595, 2020).
smallpox (1 paper, 2021). A condition that is caused by infection with Variola, and that is characterized by small, raised bumps. "In this work, we describe the generation and characterization of a VACV recombinant expressing IRF-3 that was initially prepared in the attempt to design a safer vaccine against smallpox." (PMID 34696416, 2021).
T-cell lymphoma (1 paper, 2023). "Cross-referencing the Degrabase dataset against the mtRNA signaling pathway identified in this study reveals MAVS and IRF3 as potentially relevant targets for apoptotic caspase cleavage in Jurkat T-cell lymphoma cells." (PMID 36918588, 2023).
urothelial carcinoma (1 paper, 2022). A malignant neoplasm derived from the transitional epithelium of the urinary tract (urinary bladder, ureter, urethra, or renal pelvis). "It was reported that low IRF3 was associated with poor disease free survival and overall survival in urothelial carcinoma." (PMID 35012444, 2022).
uveitis (1 paper, 2016). An inflammatory process affecting a part of or the entire uvea. "We carried out a two-stage case control study to investigate the association of 13 SNPs of TRIM20, IRF3, IRF7, IRF8, MYD88 and NF-κB1 in two different uveitis entities." (PMID 26794091, 2016).
Varicose veins (1 paper, 2023). Enlarged and tortuous veins. "IRF3 might increase the risk of varicose veins through inflammation, which is consistent with our findings." (PMID 37404740, 2023). "The COLEC11, IRF3, LUM, POSTN, RSPO3, and SARS2 were considered to share the same variant of varicose veins." (PMID 37404740, 2023). "The colocalization analysis indicated that COLEC11, IRF3, LUM, POSTN, RSPO3, and SARS2 shared the same causal variant with varicose veins." (PMID 37404740, 2023). "As a result, eight proteins were found to be causally associated with varicose veins, including COLEC11, IRF3, LUM, POSTN, RPN1, RSPO3, SARS2, and VAT1." (PMID 37404740, 2023). "We identified eight plasma proteins that are significantly associated with the risk of varicose veins after Bonferroni correction (P < 2.495 × 10−5), with five being protective (LUM, POSTN, RPN1, RSPO3, and VAT1) and three harmful (COLEC11, IRF3, and SARS2)." (PMID 37404740, 2023). "Five of eight proteins in primary analysis were finally identified as potential drug targets for varicose veins, including IRF3, LUM, POSTN, RSPO3, and SARS2." (PMID 37404740, 2023). "A comprehensive analysis indicated that IRF3, LUM, POSTN, RSPO3, and SARS2 might be potential drug targets for varicose veins." (PMID 37404740, 2023).
viral hepatitis (1 paper, 2024). An acute or chronic inflammation of the liver parenchyma caused by viruses. "Notably, the search results in the PPI network of key target protein of the intersection targets showed that TLR3, TBK1, IRF3, IL6, were important targets associated with viral hepatitis." (PMID 38322849, 2024). "Besides, TLR3, TBK1, IRF3, IL6, were important targets associated with viral hepatitis." (PMID 38322849, 2024).
infection (709 papers, 2007 to 2026). The state of being infected such as from the introduction of a foreign agent such as serum, vaccine, antigenic substance or organism. "Infection with A. actinomycetemcomitans caused a significant upregulation in the expression levels of Isg15, Mx1, Mx2, Irf3, Irf7, Tlr-2, Tnf-α, Cxcl-1, and Il-6 genes." (PMID 37929187, 2023). "Consistently, immunoblotting results showed that the levels of phosphorylated STING, TBK1 and IRF3 stimulated by HSV1-GFP infection were decreased in Ptk2b-deficient cells compared with wild-type control cells." (PMID 37989995, 2023). "Of note, the infection caused significant upregulation in mRNA expression level of interferon-stimulated genes (Isg15, Mx1, Mx2, Irf3, and Irf7) and pro-inflammatory cytokines (Tnf-α, Cxcl-1, and Il-6 genes)." (PMID 37929187, 2023). "PSCdMs were also pre-treated with poly(I:C) prior to infection, to assess how IRF3 deficiency affects the induction of an antiviral state." (PMID 35027054, 2022). "IFI16 deficiency inhibited IRF3 activation- and NF-κB-dependent gene production induced by transfected DNA, and during infection with either MVA or HSV-1." (PMID 34356829, 2021). "Deficiency of IRF3/7 results in severe mortality to infection with West Nile virus (WNV), Chikungunya virus (CHIKV), and Ross River virus infection, and promotes viral persistence in the infected hosts." (PMID 32731586, 2020). "This study also demonstrated that MEFs deficient in ADAR1 expression exhibited elevated IRF3 phosphorylation following infection with SeV or stimulation with pI:C, indicating increased activation of the RIG-I pathway." (PMID 32898178, 2020). "In accordance with IRF3 playing a role in protective immunity against the PC, IRF3-deficient mice displayed increased mortality upon PC infection as compared with IRF3-sufficient littermates, with mice heterozygous for IRF3 having intermediate survival." (PMID 32393794, 2020). "To further assess if these transcription factors specifically regulate lfTSLP transcription in hMPV-infected cells, we treated WI-38 cells with siRNAs targeting RelA (which encodes the NF-κB p65 subunit) or IRF3 prior to infection." (PMID 29343779, 2018). "This is evidenced by resistance of IFNAR- or IRF3-deficient mice to infection and more severe infection upon type I IFN induction via polyI:C treatment." (PMID 28529959, 2017). "Mosquito-mediated infection of interferon receptor 3 and 7 deficient (IRF3/7-/-) mice has been reported for dengue virus, with IRF3/7-/- mice also highly susceptible to CHIKV infection due to their inability effectively to generate type I interferon responses." (PMID 27760560, 2016). "Mice that lack the type I IFNαβ receptor-deficient (Ifnar1-/-) have been shown to be more resistant to infection with L. monocytogenes compared with wild type (WT) mice, as have mice deficient for the downstream transcription factor IRF3." (PMID 26918359, 2016). "Further, knock down of MST1/2 by Stk4/Stk3 siRNA in RAW264.7 and THP1 macrophages also led to a significant loss in infection-driven IRF3 activation." (PMID 27883091, 2016). "Double IRF-3/IRF-7 deficient mice infected with PbA were resistant to ECM upon infection confirming a role for IFN-I in ECM." (PMID 25157202, 2014). "This correlated with virus control as infected wild- type, MAVS and IRF3/7 deficient epithelia had similar virus titers over the course of infection." (PMID 24278020, 2013). "Q-B also contains the IKK complex; however, IKKα/IKKβ double-deficient MEF cells activated IRF3 normally in response to infection by vesicular stomatitis virus (VSV), an RNA virus." (PMID 23951545, 2013). "We showed that infection with Sendai virus enriched the association of IRF3 with IFNβ promoters in MEFs from wild type mice, which was maximal after 2 h, but this did not occur in MEFs from the DEAF1−/− mice." (PMID 23846693, 2013).